RNU6-756P (RNA, U6 small nuclear 756, pseudogene)
Gene: Small nuclear RNA gene on chromosome 8 (124,260,646 to 124,260,752, forward strand). Ensembl gene ENSG00000206724.
Homologues: Orthologues: chimpanzee U6 (95% identical), macaque U6 (93% identical), dog U6 (92% identical), pig U6 (90% identical), rat U6 (86% identical). Paralogues in human: RNU6-140P (92% identical), RNU6-25P (91% identical), RNU6-29P (91% identical), RNU6-33P (91% identical), RNU6-1 (90% identical), RNU6-116P (90% identical), RNU6-2 (90% identical), RNU6-22P (90% identical), RNU6-35P (90% identical), RNU6-38P (90% identical), RNU6-39P (90% identical), RNU6-3P (90% identical), and 1287 more.